CXCR1 (C-X-C motif chemokine receptor 1)
Diseases named in the same sentence as CXCR1 in open-access papers (continued):
Sharing a sentence is not in itself a finding about the gene and the disease.
melanoma (continued). "Collectively, presented here data demonstrate that Ladarixin, a dual CXCR1/2 small molecule inhibitor, has a multifactorial effect on melanomas in vitro and in vivo independently of the genetic defects underlying tumorigenic phenotype." (PMID 28129639, 2017). "Previous studies demonstrated that CXCR1/2 receptors are expressed by microvascular endothelial cells and that secretion of CXCR1/2 ligands by melanoma enhances de novo angiogenesis." (PMID 28129639, 2017). "Blocking IL-8 significantly impaired the proliferative effect of phEC-CM on human A375 melanoma cells, consisting with the inhibition of IL-8 receptors CXCR1 and CXCR2 by using specific small molecular inhibitor SB225002." (PMID 26762853, 2016). "In melanoma, knockdown of the receptors or the use of antagonists or neutralizing antibodies against CXCR1/2 affected cell proliferation, migration and tumor growth, strongly indicating the involvement of these receptors in melanoma progression." (PMID 23420470, 2013). "Our previous studies have shown that exogenous CXCL-8 stimulated extracellular signal-regulated kinases (ERK) phosphorylation in melanoma cell lines, which is involved in CXCR1- or CXCR2-mediated cell growth." (PMID 23342280, 2012). "The expression of CXCL8 in melanoma, as well as its receptors CXCR1 and CXCR2, has demonstrated a positive correlation with disease progression." (PMID 24212647, 2011). "CXCL8, acting as an autocrine/paracrine growth factor, influences the process of melanoma progression by activating its receptors, CXCR1 and CXCR2." (PMID 24212647, 2011). "Our results clearly showed a decrease in cell growth of CXCR1 or CXCR2 overexpressing A375P melanoma cells on treatment with the inhibitor." (PMID 19401689, 2009). "Immunohistochemical analyses showed significantly increased tumour cell proliferation and microvessel density and reduced apoptosis in tumours generated from CXCR1- or CXCR2-overexpressing melanoma cells." (PMID 19401689, 2009). "The aggressiveness of malignant melanoma is associated with differential expression of CXCL-8 and its receptors, CXCR1 and CXCR2." (PMID 19401689, 2009). "CXCR1- or CXCR2-induced modulation of melanoma cell proliferation and migration was observed to be mediated through the activation of ERK1/2 phosphorylation." (PMID 19401689, 2009). "Here, we have also demonstrated that overexpression of CXCR1 or CXCR2 in CXCL-8-expressing melanoma cells potentiates ERK1/2 MAP kinase signalling." (PMID 19401689, 2009). "We have previously demonstrated that the treatment of mice bearing genetically derived inducible melanoma tumors (BRAF/PTEN or NRAS/INK4a) with the CXCR1/2 antagonist (SX-682) inhibited tumor growth and increased activated CD8+ T cells, partly by reducing the intratumoral MDSCs." (PMID 40904502, 2025). "Altogether, these data suggest that the addition of the CDK2 inhibitor to CDK4/6 and CXCR1/2 inhibitors not only reduces melanoma tumor cell viability and tumor growth more effectively in BRAFWTNRASWT melanoma cells but also results in a less immunosuppressive tumor immune microenvironment." (PMID 40904502, 2025). "In this study, we evaluated the effectiveness of the CDK4/6 inhibitor, palbociclib, the CDK2 inhibitor, PF-07104091, the dual CXCR1 and CXCR2 (CXCR1/2) antagonist, SX-682, and the combination of these inhibitors for effective treatment of melanoma in preclinical models." (PMID 40904502, 2025). "Since melanoma is a skin cancer and chemokines participate in its progression, utilizing previous strategy in the modulation of CXCR1/CXCR A study was developed to design a novel PSMA–PI3K small patch drug conjugate known through affecting Pi3K/AKT can further enhance its treatment." (PMID 40740483, 2025).
melanoma (continued). "Accordingly, studies in vitro and in animal models have demonstrated that the IL-8/CXCR1/2 axis can support melanoma growth and metastasis, both directly, sustaining autocrine loops of proliferation and invasiveness, and indirectly, promoting angiogenesis and immunosuppression." (PMID 39143551, 2024). "When Cxcr1/Cxcr2 were antagonized in Braf/Pten mice and tumorigenic melanoma cell lines via treatment with SX-682, similar alterations in tumor growth and the gene expression profiles were achieved, and this was accompanied by development of anti-tumor immune microenvironment." (PMID 37270599, 2023). "Moreover, CXCR1/CXCR2 antagonists combined with anti-PD-1 are currently in clinical trials for the treatment of melanoma (NCT03161431)." (PMID 37270599, 2023). "Our data support combining CXCR1/CXCR2 antagonists with immunotherapy for melanoma patients." (PMID 37270599, 2023). "To validate the role of pro-tumor neutrophils/G-MDSCs in our model, we next measured the effect of treating lesion-bearing animals with SX-682, a small molecule inhibitor of CXCR1/2 reported to target G-MDSCs (currently in phase I trials for melanoma, NCT03161431)." (PMID 34408137, 2021). "Immunohistochemical analyses of patient samples show an increased expression of CXCL8 and its receptors as melanomas transition from a radial (early stage) to vertical (later stage) growth phase, with CXCR1 upregulation being a key genetic difference between benign naevi and malignant melanoma." (PMID 34830780, 2021). "In relation to this angiogenic property, it was reported that when CXCL1 produced by melanoma cells binds to CXCR1 or CXCR2 receptors expressed in endothelial cells, it can induce the recruitment of these cells to the tumor microenvironment, leading to the formation of new vessels." (PMID 31374840, 2019). "Interestingly, another CXCR1/2 inhibitor, Ladarixin, was shown to significantly reduce human melanoma cell motility and to induce apoptosis in vitro." (PMID 30420855, 2018). "Secretion of chemokines from these cells and from primary dark- and light-pigmented primary human melanocytes (1256b and 1603c, respectively) assessed by chemokine antibody array showed that levels of CXCR1/2 ligands were higher in all but one (WM164) melanoma lines as compared to melanocytes." (PMID 28129639, 2017). "To assess whether LDX-mediated CXCR1/2 blocking affects NF-kB activity, we generated several melanoma cell lines stably expressing NanoLuc® luciferase under the control of the NF-κB response elements." (PMID 28129639, 2017). "CXCL8 (IL-8) signaling has been implicated in STAT3 activation and nuclear translocation, suggesting that inhibition of CXCR1/2 may also lead to the inhibition of STAT3 in melanoma cells." (PMID 28129639, 2017). "Here, to test if A2058 metastatic melanoma cells use signalling pathways through IL-8 receptors C-X-C chemokine receptor type (CXCR)-1 and C-X-C chemokine receptor type (CXCR)-2 to induce gap formation in endothelial monolayers, we used neutralizing antibodies against these receptors." (PMID 28393886, 2017). "Inhibition of human melanoma growth by CXCR1 antagonist has been reported." (PMID 22936990, 2012). "Ectopic expression of CXCR1 or CXCR2 confers a more aggressive phenotype to melanoma cells." (PMID 19401689, 2009). "Moreover, an increase in chemotaxis and chemoinvasion of human melanoma cells expressing CXCR1 or CXCR2 on stimulation with CXCL-8 was also observed." (PMID 19401689, 2009). "In addition, our data demonstrated that the CXCL-8-induced and CXCR1- or CXCR2-dependent modulation of melanoma cell proliferation and migration was mediated through the ERK1/2 MAP kinase pathway." (PMID 19401689, 2009). "In addition to melanoma cells, both CXCR1 and CXCR2 are differentially expressed on endothelial cells." (PMID 19401689, 2009).
melanoma (continued). "In melanoma, it is known to drive the production of Interleukin-1 beta (IL-1β), which sustains chemotherapy-resistant cells through an IL-1β/Interleukin-8 (IL-8)/C-X-C motif Chemokine Receptor 1 (CXCR1) signaling circuit, establishing a response that reinforces tumor growth and survival." (PMID 40445912, 2025). "Elevated levels of CXCR1 or CXCR2 have been associated with increased melanoma cell proliferation and invasion, whereas inhibition of these receptors has been shown to impede melanoma cell growth, movement, and vascularization both in laboratory settings and animal models." (PMID 40124384, 2025). "Moreover, the disruption of CXCR1/2 through SX-682 has shown efficacy in mice, and its combinatorial treatment with PD-L1-targeted antibody, pembrolizumab, is also being studied in a phase 1 trial in melanoma (NCT03161421)." (PMID 36091114, 2022). "However, redundancy of chemotactic signals presents a significant challenge in designing therapeutic strategies to attenuate the effects of CXCR1/2 signaling on melanoma cells and tumor microenvironments, and the pre-requisites for the successful treatment remain undefined." (PMID 28129639, 2017). "As expected, SB225002, an inhibitor of CXCR1 and 2 receptors, or CM of senescent fibroblasts silenced for GCP‐2, significantly reduced the migratory response of A375 melanoma cells." (PMID 41258756, 2025). "The significant inhibition of proliferation, migration, and invasion of melanoma cells by SCH‐527123 through the downregulation of CXCR1 and CXCR2 and suppression of the PI3K/AKT pathway suggests its potential as a therapeutic agent for melanoma." (PMID 40740483, 2025). "SCH‐527123, a small‐molecule antagonist of CXCR1 and CXCR2, was found to significantly inhibit proliferation, migration, and invasion of human melanoma cell lines A375 and M14, while promoting apoptosis." (PMID 40740483, 2025). "While shRNAs have previously been used to knock down CXCR1 and CXCR2 in a human melanoma cell line showing inhibition of tumor growth and microvessel density, these experiments were performed in immune deficient mice and with only one cell line." (PMID 37270599, 2023). "The major chemokine/chemokine receptor interactions occurring in melanoma development and progression include the CXCR4/CXCR7/CXCL12, CXCR3/CXCL9,10,11, CXCR1,2/CXCL8, CCR2/CCL2, CCR4/CCL17,22, CCR5/CCL5, CCR7/CCL21 and CCR10/CCL27 axes." (PMID 37170733, 2023). "It has previously been demonstrated that CXCR1 activation mediates chemotaxis, whereas CXCR2 activation promotes angiogenesis, invasion and migration of human melanoma cells." (PMID 37170733, 2023). "Melanoma cells constitutively released CXCL8/IL-8, CXCL1/Groα and CXCL2/Gro-β, and CM induced PMN chemotaxis was dependent on CXCR1/2 activation." (PMID 37525065, 2023). "The CXCR1/CXCR2 ligand-receptor axis has been widely characterized as a driver of aggressive behavior in many cancer types, including breast, prostate, melanoma, lung, colorectal, pancreatic, and renal cancers." (PMID 37270599, 2023). "Using the available Gene Expression Omnibus (GEO) cohort, we evaluated CXCR1, CXCR2, and CXCL1-3, 5 and 8 (CXCR1/CXCR2 ligands) expression in nevi and melanoma." (PMID 37270599, 2023). "The corresponding ligand to CXCR1 and CXCR2, namely CXCL8, is overexpressed on various cancer cells, including melanoma." (PMID 37170733, 2023). "In melanoma, inhibition of FTO suppresses tumorigenicity and increases the m6A levels in PD-1, CXCR1, and SOX10, hence enhancing the decay of these m6A-targeted mRNAs by YTHDF2." (PMID 35254013, 2022). "The most significant chemokine in angiogenesis in melanoma is CXCL8, which can have paracrine and autocrine effects when it binds to CXCR1 and CXCR2, expressed on melanoma cells and endothelial cells within the TME." (PMID 34830780, 2021).
melanoma (continued). "CXCR1 and CXCR2-overexpressing tumours show an increased proliferation of melanoma cells and increased microvessel density, with evidence of reduced apoptosis in both cell lines in in vitro and in vivo models." (PMID 34830780, 2021). "When the CXCR1/CXCR2 signalling pathway is blocked, new vessel formation is greatly reduced, and melanoma growth is inhibited." (PMID 34830780, 2021). "For example, malignant melanomas express higher levels of CXCL1, CXCL2, and CXCL8 and receptors CXCR1, CXCR4, CCR10, and CCR7 compared with benign naevi." (PMID 34830780, 2021). "Together this suggests that CXCR1 and CXCR2 inhibition is an attractive intervention strategy for malignant melanoma." (PMID 34458892, 2020). "A currently recruiting Phase I clinical trial (NCT03161431) will treat participants with melanoma for 21 days with SX-682, a CXCR1/2 inhibitor, as a monotherapy - then with pembrolizumab, an FDA approved immunotherapy for melanoma." (PMID 34458892, 2020). "Its role in the progression of melanoma mainly depends on its interaction with specific cell surface G protein coupled receptor (GPCR), C-X-C chemokine receptor type 1 (CXCR1) and C-X-C chemokine receptor type 2 (CXCR2)." (PMID 32894090, 2020). "Inhibition of CXCR1/2 by SCH-527123 restrained cell proliferation, migration and invasion in melanoma." (PMID 30984000, 2019). "Downregulation of CXCR1 and CXCR2, by interfering siRNA, inhibits melanoma tumor growth and cell invasion; similarly RNAi of GROα suppresses tumor growth in hepatocellular carcinoma." (PMID 29081734, 2017). "In this pre-clinical study we investigated the capacity of a novel small molecule dual CXCR1/2 inhibitor, Ladarixin (LDX), to attenuate progression of experimental human melanomas." (PMID 28129639, 2017). "Limited number of reports on targeted inhibition of Gro family chemokines, CXCL8 (IL-8) and their receptors (CXCR1 and CXCR2) in various tumor models including melanomas, suggested a potential applicability of these approaches for tumor growth inhibition." (PMID 28129639, 2017). "Recently, CXCR1 and CXCR2 antagonist are used to treat human melanoma, lung, breast, and pancreatic cancer growth by inhibiting tumor cell proliferation and suppression of angiogenesis and metastasis." (PMID 28484461, 2017). "Considering involvement of the CXCR1/2 signaling in migration, the effect of the LDX on motility of melanoma cells was examined using in vitro migration/scratch assay." (PMID 28129639, 2017). "SCH-527123 and SCH-479833, dual CXCR1/2 and CXCR2 antagonists, were shown to inhibit migration and proliferation of A375SM melanoma cells." (PMID 28129639, 2017). "In a screen of several melanoma cell lines it was detected that the expression of chemokine receptors CCR7, CCR10, CXCR1, CXCR2 and CXCR4 can dramatically increase the rate of metastases and define their preferential site." (PMID 26197340, 2015). "Previous studies have indicated that CXCR1/2 expression is significantly correlated with invasion, metastasis and advanced TNM stage in patients with malignant melanoma and prostate cancer." (PMID 23420470, 2013). "Our recent studies have demonstrated that CXCR1 and CXCR2, receptors of CXCL-8, are functionally involved in melanoma progression." (PMID 23342280, 2012). "Two high-affinity receptors for CXCL-8, CXCR1 and CXCR2, are differentially expressed on melanoma and endothelial cells." (PMID 23342280, 2012). "Over-expression of CXCR1 and CXCR2 in melanoma cells conferred an aggressive phenotype to melanoma cells based on enhanced proliferation, migration, and tumor growth in mice." (PMID 24212647, 2011). "Previously, we showed that targeting of chemokine receptors, CXCR1 and CXCR2, in malignant melanoma by small-molecule antagonists led to reduced tumour growth, invasion, and angiogenesis." (PMID 21045835, 2010). "CXCR1 and CXCR2 are expressed by melanoma and are involved in melanoma proliferation and metastasis." (PMID 24281094, 2010).
melanoma (continued). "In conclusion, our results suggest that CXCR1 and CXCR2 play important roles in the regulation of human melanoma tumourigenesis and progression." (PMID 19401689, 2009). "On the other hand, a recent report suggests that in melanoma cells, CXCL-8-mediated chemotaxis is mainly mediated through CXCR1." (PMID 19401689, 2009). "Having seen the observable differences in tumourigenicity, we next performed in vitro assays to examine the effect of CXCR1 and CXCR2 overexpression on the growth and malignant behaviour of melanoma cells." (PMID 19401689, 2009). "In this study, we demonstrated the functional significance of CXCR1 and CXCR2 expression in melanoma growth, tumourigenesis, motility and invasion." (PMID 19401689, 2009). "Together, these studies demonstrate that CXCR1 and CXCR2 play essential role in growth, survival, motility and invasion of human melanoma." (PMID 19401689, 2009). "Our data demonstrated that CXCR1- or CXCR2-overexpressing SBC-2 and A375P melanoma cells had enhanced proliferation, chemotaxis and invasiveness in vitro." (PMID 19401689, 2009). "In this study, we investigate the precise functional role of CXCR1 and CXCR2 in melanoma progression." (PMID 19401689, 2009). "The aggressiveness of malignant melanoma is attributed, in part, to the expression of CXCL-8 and its receptors, CXCR1 and CXCR2." (PMID 19401689, 2009). "The chemokines CXCL1 (Gro-α) and CXCL8 (IL-8) are constitutively produced by melanoma cells and the corresponding receptors CXCR1 and CXCR2 are expressed on melanoma cells as well as on macrophages, neutrophils and eosinophils." (PMID 16052222, 2005). "Targeting GCP‐2 or the CXCR1 and CXCR2 receptors relaying signals of GCP‐2 to activate CREB or CREB itself might be a unique possibility to suppress melanoma progression in old patients." (PMID 41258756, 2025). "Interestingly, both recombinant GCP‐2 and, to a lesser extent, ENA‐78 stimulated anchorage‐independent growth of melanoma cells, which was inhibited following either immunodepletion of GCP‐2, ENA‐78, or treatment with the CXCR1/2 inhibitor SB225005." (PMID 41258756, 2025). "In addition, the effects of a CXCR1/CXCR2 antagonist, SX-682, on melanoma tumorigenesis were evaluated in BrafV600E/Pten−/− and NRasQ61R/INK4a−/− mice and in melanoma cell lines." (PMID 37270599, 2023). "In addition, the inhibition of the CXCR1,2/CXCL8 axis in mouse models reduced melanoma infiltration by neutrophils, tumour growth, angiogenesis and metastasis." (PMID 37170733, 2023). "In addition to the effect of the CXCR1,2/CXCL8 axis in melanoma cells, it also plays an essential role in immune regulation as CXCR1 and CXCR2 are expressed on neutrophils, correlating with poorer prognosis and poor response to checkpoint inhibition." (PMID 37170733, 2023). "The ABCB5 drug efflux transporter, a marker for slow-cycling melanoma cells, was shown to be related to the expression of CXCR1 but not CXCR2." (PMID 36831112, 2023). "The chemokine receptors CXCR1 and CXCR2 are expressed on granulocytes, monocytes, mast cells, NK cells, neutrophils, basophils, CD8+ Teff cells and endothelial cells, whereas being overexpressed in melanomas." (PMID 37170733, 2023). "Notably, inhibition of both CXCR1 and CXCR2 was necessary to block PMN chemotaxis, highlighting the pleiotropic and redundant potential of melanoma-derived chemokines." (PMID 37525065, 2023). "CXCR1 (C-X-C chemokine receptor 1) interacting with CXCL8 (Interleukin-8, IL-8) ligand has a well-known role in the initiation and development of various cancers, including melanoma." (PMID 37240247, 2023). "Several studies found that upregulation of CXCR1 or CXCR2 resulted in an increase of melanoma cell proliferation and invasion, while knockdown of CXCR1 and/or CXCR2 led to inhibition of melanoma cell growth, motility, and vascularization both in vitro and in vivo." (PMID 36612163, 2022).